PPP4R1L (protein phosphatase 4 regulatory subunit 1 like (pseudogene))
Description:
May be a regulatory subunit of serine/threonine-protein phosphatase 4.
Synonyms: bA196N14.4; bA196N14.5; PPP4R1P1; formerly C20orf192
Gene: Transcribed unprocessed pseudogene on chromosome 20 (58,231,789 to 58,286,399, reverse strand). Ensembl gene ENSG00000124224.
Diseases named in the same sentence as PPP4R1L in open-access papers:
PPP4R1L is named in the same sentence as 3 diseases in open-access papers, as found by Europe PMC text mining. Sharing a sentence is not in itself a finding about the gene and the disease. The quoted sentences say what the papers report.
prostate carcinoma (1 paper, 2019). A carcinoma that arises from epithelial cells of the prostate gland. "hsa-miR-375 is associated with docetaxel resistance in prostate cancer and PPP4R1L knock-down in HeLa cells induces taxol resistance." (PMID 31029062, 2019). "For instance, both PPP4R1L pseudogene and SOX15 are DE in prostate cancer and associated with hsa-miR-375." (PMID 31029062, 2019). "Both SOX15 and PPP4R1L are likely regulated by hsa-miR-375 based on the TCGA prostate cancer dataset." (PMID 31029062, 2019). "PPP4R1L and SOX15 are significantly co-expressed (Pearson correlation coefficient = 0.51, P-value < 2.2 × 10−16) in tumor tissue but much less correlated in normal controls in prostate cancer (Pearson correlation coefficient = 0.24, P-value = 0.09)." (PMID 31029062, 2019).
cancer (1 paper, 2019). A tumor composed of atypical neoplastic, often pleomorphic cells that invade other tissues. "PPP4R1L is also located in a region associated with high mutation rates in cancer cell lines, which could be indicative of mutational “on/off switches” in pseudogene regulation." (PMID 31029062, 2019).
tumor (1 paper, 2019). "PPP4R1L and SOX15 are both significantly DE between tumor and normal controls (Bonferroni-corrected P-value = 3.42 × 10−7, 2.01 × 10−14, respectively)." (PMID 31029062, 2019).